INS (insulin)
Diseases named in the same sentence as INS in open-access papers (continued):
Sharing a sentence is not in itself a finding about the gene and the disease.
Insulin resistance (continued). "In adipose tissue, insulin resistance impairs the anti-lipolytic activity of insulin, leading to an exacerbated lipolysis that increases circulating free fatty acids (FFAs)." (PMID 37513560, 2023). "In T2D models of HFD or acute S961 insulin resistance, senescence results in an accelerated aging phenotype in β-cells and dramatically impairs insulin secretion." (PMID 37720527, 2023). "In kidney disease, insulin resistance can lead to diminished sensitivity of peripheral tissues, including muscle and adipose cells, towards insulin." (PMID 37868469, 2023). "Studies have confirmed that obesity and insulin resistance are significantly correlated with the level of oxidative stress, and oxidative stress can inhibit the insulin signaling pathway." (PMID 37576042, 2023). "This normalization cascade culminates in an amelioration of insulin resistance and an augmentation of insulin sensitivity." (PMID 37964962, 2023). "In the current study, acute UCN2 dosing agonizes CRHR2 causing insulin resistance in the skeletal muscle, whereas chronic, elevated levels of UCN2 desensitize CRHR2 leading to the opposite: insulin sensitization." (PMID 37402735, 2023). "The main manifestation of SRS was insulin resistance (IR), wherein the target organs, tissues, or cells showed reduced sensitivity and responsiveness to insulin." (PMID 37794331, 2023). "Type 2 diabetes (T2D) develops due to insulin resistance and an inability of the pancreatic β-cells to increase secretion of insulin and reduce elevated blood glucose levels." (PMID 36869830, 2023). "In a state of insulin resistance, pancreatic beta cells continue to produce excessive insulin, resulting in oxidative stress." (PMID 37959125, 2023). "Recent findings have demonstrated uric acid’s role in influencing insulin secretion by escalating oxidative stress in β cells, thereby triggering insulin resistance." (PMID 38034019, 2023). "For example, in diabetic patients given yogurt containing L. acidophilus La5 and B. lactis Bb12 as probiotics, fasting blood glucose, insulin, insulin resistance, and glycosylated hemoglobin levels were reduced." (PMID 37175825, 2023). "Insulin resistance (IR) is defined as reduced insulin sensitivity and refers to an increased amount of insulin needed to perform its metabolic actions." (PMID 37432289, 2023). "In this sense, in some clinical trials, it has been reported that, with doses between 200 and 1000 mg/day of RV, the levels of glucose, insulin, HbA1c and insulin resistance are reduced in subjects with T2D younger than 50 years." (PMID 37108584, 2023). "Rac1 appears to be essential for insulin signaling in muscle glucose uptake, which implicates Rac1 in human insulin resistance and dysglycemia." (PMID 37566054, 2023). "β-Cell adaptation to insulin resistance is regulated by the interplay of signals from growth factors, cytokines, insulin, and nutrients such as glucose, fatty acids, and amino acids (AAs)." (PMID 37423392, 2023). "HGF is considered an important component of the pathophysiology of insulin resistance, regulating the metabolic flux of glucose in different insulin-sensitive cell types and playing a role in β-cell homeostasis." (PMID 37170115, 2023). "The improvement in the fasting blood glucose and fasting serum insulin profile can eventually lead to improvement of insulin resistance, which was reflected in our study in the homeostatic model assessment (HOMA) index." (PMID 36677541, 2023). "Insulin resistance (IR) is defined as any decrease in tissue response to the stimulatory effects of insulin, resulting in an imbalance in glucose metabolism, oxidative stress, and an inflammatory reaction." (PMID 36846644, 2023). "Insulin is a regulator of the mTOR complex and insulin resistance in obese rats stimulated the mTOR1 complex in the liver and muscle tissue, through increased expression of PI3Ks/Akt signalling." (PMID 37275420, 2023).
Insulin resistance (continued). "The importance of asprosin as an early marker of insulin resistance requires further research with direct measurement of insulin sensitivity." (PMID 37371663, 2023). "In animal studies, traffic-related air pollution (TRAP) was shown to elicit oxidative stress and subclinical inflammation, resulting in impaired insulin signaling and insulin resistance." (PMID 37325174, 2023). "As a result of insulin resistance developing in this patient group, the amount of endogenously produced insulin begins to be insufficient and exogenous insulin is added to the treatment regimen." (PMID 36984506, 2023). "An important aspect of this is changes in maternal insulin sensitivity (IS) and insulin resistance (IR) that is mediated by a range of maternal, placental, and fetal hormones." (PMID 36676079, 2023). "These inflammatory factors can stimulate the inflammatory response and interfere with insulin signaling, leading to insulin resistance." (PMID 37649550, 2023). "Of particular concern is the increasing incidence of type 2 diabetes, the primary causes of which are obesity-driven insulin resistance in white adipose tissue (WAT), skeletal muscle, and liver, and decreased insulin secretion by pancreatic β-cells." (PMID 39872858, 2023). "Glucose intolerance can arise from insufficient pancreatic insulin secretion or peripheral insulin resistance in the liver, adipose tissue, or muscle." (PMID 37691128, 2023). "Insulin resistance is a condition in which the pancreas generates enough insulin but the body is unable to use the insulin efficiently." (PMID 37038362, 2023). "CMKLR1 is linked to nuclear factor kappa-light-chain-enhancer of activated B cells (NF-κB) activation and insulin signaling, and kinesin family member 5B (KIF5B) is associated with insulin resistance and obesity." (PMID 37958793, 2023). "These four distinct mechanisms act alone or in concert to overcome insulin resistance for maintaining normoglycemia in insulin-resistant subjects with obesity." (PMID 38229396, 2023). "Hyperinsulinemia usually is accompanied by insulin resistance, but there is only partial suppression of insulin signaling, favoring lipogenesis as well as mTORC1 activation for protein synthesis and autophagy inhibition." (PMID 37854186, 2023). "While it is known that insulin resistance contributes to the progression of renal disease, we observed that reduced DNA methylation of insulin signaling genes closely corresponded to gene-activating events." (PMID 36633903, 2023). "Peripheral insulin resistance is attributed to the subsequent failure of cells to efficiently react to changing insulin levels within the various target tissues within the body." (PMID 36902074, 2023). "A high-fat diet has been shown to induce a TNF-dependent increase in circulating inflammatory monocytes that predicts increased blood insulin levels and insulin resistance." (PMID 37569635, 2023). "Adiposopathic immunopathies, endocrinopathies, and increased circulating free fatty acids contribute to multi-organ insulin resistance, as well as an ultimate decline in pancreatic beta cell insulin secretory function." (PMID 37990681, 2023). "Key contributors to tumorigenesis and tumor progression include hyperglycemia, insulin resistance, and increased levels of insulin and insulin-like growth factors as well as increased adipocytokines associated with obesity." (PMID 39516686, 2023). "Insulin resistance, which is defined as a suboptimal response to normal blood levels of insulin, is what links overweight and obesity to worsening pancreatic β cell function, T2D and its associated metabolic consequences such as cardiovascular diseases." (PMID 37021835, 2023). "The targets of this miRNA are the different key genes involved in insulin signaling, insulin resistance, fatty acid, triglyceride, lipoprotein and cholesterol biosynthesis and NAFLD." (PMID 36875756, 2023).
Insulin resistance (continued). "The term “cerebral insulin resistance” describes the inability of brain cells to respond to insulin as they normally would, resulting in impaired synaptic, metabolic, and immune function." (PMID 37239922, 2023). "In T2DM, insulin-sensitive tissues gradually lose insulin sensitivity resulting in insulin resistance and significantly contributing to T2DM complications." (PMID 37715850, 2023). "The predominant mechanism in lean diabetic patients was impaired insulin secretion, whereas that for obese subjects was insulin resistance." (PMID 37792730, 2023). "Patients with FPLD develop metabolic abnormalities including hypertriglyceridemia, insulin resistance, and diabetes mellitus, which are difficult to manage with conventional therapies including fibrates, statins, and insulin." (PMID 36689070, 2023). "Canonically, insulin-stimulated GLUT4 translocation is facilitated by a signalling cascade comprising PI3K/Akt and dysfunction in this pathway has been implicated in insulin resistance, although this is controversial." (PMID 37494090, 2023). "Additionally, arsenic influences the expression of genes associated with insulin resistance, causing cells to deviate from their normal differentiation pathway and shift towards the proliferation pathway, which affects the sensitivity of peripheral tissues to insulin." (PMID 37759824, 2023). "In the liver of FA the increased P-IRS levels on Serine 307 confirms the impaired insulin response and insulin resistance occurring in the liver." (PMID 36875756, 2023). "In addition, liver-specific Zfyve28 overexpression in mice impaired insulin sensitivity and caused an increase in lipid content in the serum and liver, while Zfyve28 liver-specific knockout in mice significantly improved insulin sensitivity and relevant indicators associated with insulin resistance." (PMID 37884540, 2023). "HFD impaired islet cell function and triggered insulin resistance in mice, as reflected by the increased INS and HOMA-IR levels, as well as the decreased HOMA-β levels in the HFD group." (PMID 37693249, 2023). "T2DM is characterized by dysregulation of carbohydrate, lipid, and protein metabolism; which occurs from decreased insulin secretion, insulin resistance, or a combination of the two; usually occurs later in life; and is frequently linked to lifestyle factors." (PMID 38004353, 2023). "Insulin resistance was induced in the skeletal muscle cells after 4 h of exposure to palmitic acid (0.5 mmol/L), and then treated with either insulin (4 μg/mL) or bredemolic acid (12.5 mmol/L) or with both." (PMID 38099180, 2023). "Those in the mixed group have severe hepatic, muscular insulin resistance and reduction in insulin secretion." (PMID 36950879, 2023). "On the other hand, the combined use of STZ and WD appears to produce a more complex diabetic phenotype characterized by a combination of impaired insulin secretion and peripheral insulin resistance." (PMID 37885804, 2023). "Fasting insulin (p = 0,034), insulin resistance (p = 0,030), total and LDL cholesterol (p = 0,023 and 0,008) reduced more in the MCRD diet than the HND." (PMID 37452403, 2023). "Specifically, APCs ameliorate insulin resistance by improving hepatic insulin signaling through the suppression of hepatic inflammation in ob/ob mice." (PMID 37009462, 2023). "It further suggested that insulin bound to more INSRs in the ovarian than in the liver and skeletal muscle in insulin resistance." (PMID 37830511, 2023). "It has been reported that people with obesity develop insulin resistance, which hinders insulin in performing its cellular actions." (PMID 37103396, 2023). "Second, limited by GWAS, we decided to use fasting insulin levels as a proxy for insulin resistance." (PMID 37900148, 2023). "In the progression of hypertension and T2DM, increased inflammatory cytokines impair insulin secretion and sensitivity and induce insulin resistance and β-cell dysfunction." (PMID 37752554, 2023).
Insulin resistance (continued). "Insulin resistance is a phenomenon in which this action of insulin is weakened and blood glucose concentration increases." (PMID 36834911, 2023). "The overabundance of circulating fatty acids lead to insulin resistance, and the aggravation of insulin resistance can further inhibit the antilipolytic effect of insulin and increase lipolysis." (PMID 37033250, 2023). "Insulin resistance (IR) presents as cells’ decreased sensitivity to insulin; in this condition, the body cells cannot correctly use the available insulin, leading to higher levels of blood glucose." (PMID 36651702, 2023). "Polycystic ovarian syndrome (PCOS) is a women’s endocrine condition with more susceptibility to insulin resistance and T2DM, of which one common treatment is insulin sensitizers." (PMID 36911663, 2023). "The more severe the insulin resistance, the more dysfunctional the islet β cells are, the more changes in insulin signaling proteins in exosomes are, and these exosomes are preferentially absorbed by white blood cells." (PMID 36818396, 2023). "Inflammatory cytokines produced by adipose tissue can impair insulin signaling and promote insulin resistance, further exacerbating the cycle of weight gain and metabolic dysfunction." (PMID 37600709, 2023). "Those patients have abnormal insulin resistance and increased serum glucose level that makes serum insulin level increase." (PMID 36943853, 2023). "In contrast, metformin therapy lowers insulin resistance and thus reduces insulin signaling toward SGs." (PMID 37998335, 2023). "Our MR analysis further indicated a causal effect of increased fasting insulin levels (a proxy of insulin resistance) on the risk of PCOS, which was supported by a suggestive causal effect of insulin resistance on PCOS reported in a previous MR study." (PMID 36800955, 2023). "Under conditions of insulin resistance, where insulin-dependent glucose uptake in peripheral organs is reduced, the β cells produce more insulin to compensate, leading to hyperinsulinemia." (PMID 37762083, 2023). "Hyperlipidemia promotes insulin resistance by blocking insulin signals and destroying pancreatic beta cells, giving rise to hyperglycemia." (PMID 37993853, 2023). "Metabolic parameters, such as fasting blood glucose, insulin, insulin resistance (quantified with HOMAIR), triglycerides, total cholesterol, LDL-cholesterol, ALT, γGT, and FT3 blood concentrations were lower after VLCKD." (PMID 36839183, 2023). "T2DM is a lifestyle disease characterized by an impaired insulin release, insulin resistance in various tissues, increased metaflammation, hyperglycaemia, comorbidity (e.g., CVD) increased adiposity and ectopic fat." (PMID 36844000, 2023). "The animals exhibited higher insulin levels, insulin resistance (indicated by increased HOMA-IR), lower IGF-1 levels, and increased IGF-1R phosphorylation." (PMID 37569816, 2023). "Some studies reported that the level of insulin was inversely related to handgrip strength, and patients with insulin resistance had lower handgrip strength." (PMID 37265691, 2023). "After study completion, a significant reduction in fasting insulin levels and insulin resistance was observed in the whey protein group versus glucose control diet." (PMID 36695783, 2023). "In general, insulin resistance is defined as the reduced response to insulin by target cells, due to reduced IR levels and/or activation or increased IRS1 inhibitory phosphorylation that finally results in impaired glucose uptake and cell metabolism." (PMID 36670973, 2023). "Insulin resistance manifests when this finely tuned pathway falters, impeding the profound physiological effects of insulin." (PMID 38053837, 2023). "Briefly, the melatonin-induced increase in insulin concentration occurs through the melatonin IP3 signaling pathway to compensate for the increasingly fatal insulin resistance at night in humans." (PMID 36986139, 2023).
Insulin resistance (continued). "In earlier studies, using 3TC with other ARVs caused disturbances in glucose metabolism with a significant decrease in insulin-mediated glucose disposal, thus showing the promotion of insulin resistance." (PMID 37047241, 2023). "One early and sustained feature of T2DM is insulin resistance (IR), a condition where the body cells fail to respond to normal insulin." (PMID 37362539, 2023). "There are several measurements that are used to determine if a person has insulin resistance, poor insulin secretion, and poor glucose control." (PMID 37375623, 2023). "In this state of advanced insulin resistance, the decrease in insulin lowers PI3K/AKT signaling and increases FoxO1 activity which impairs PDX1-mediated β-cell growth further reducing insulin secretion and contributing to T2D pathogenesis." (PMID 37941908, 2023). "A significant risk factor for the development of type-2 diabetes, which is characterized by elevated blood glucose levels, insulin resistance, and insufficient insulin secretion, is a high sugar intake." (PMID 38002116, 2023). "Additionally, considering the established association between BCAA and insulin resistance, the valine-induced impairment of insulin sensitivity, accompanied by an increase in glucose levels, might be a driver of the positive correlation between valine and glucose in our patients." (PMID 37759723, 2023). "Hyperinsulinemia and increased beta cell insulin production occur due to impaired glucose disposal brought on by insulin resistance." (PMID 37629550, 2023). "Six of the seventeen studies evaluated metabolic parameters such as glucose, total and HDL-cholesterol, triglycerides, glucose transporter 4 (GLUT4), insulin, insulin sensitivity index and the homeostatic model assessment-insulin resistance (HOMA-IR)." (PMID 36843041, 2023). "Increasing insulin resistance is a normal part of pregnancy as levels of insulin resistance and insulin production increase to divert glucose to the placenta and, consequently, to the foetus." (PMID 37518503, 2023). "Type 2 diabetes (T2D) is characterized by defective insulin secretion and β-cell expansion in conditions of insulin resistance." (PMID 37423392, 2023). "Insulin resistance is a metabolic state in which the liver and peripheral tissues, mainly muscles, become less responsive to insulin." (PMID 38098008, 2023). "As expected, women with AN were much leaner, had lower fasting serum concentrations of glucose and insulin, higher insulin sensitivity as estimated by homoeostatic model assessment for insulin resistance (HOMA-IR) and lower serum C-reactive protein." (PMID 37069399, 2023). "At normal fasting conditions, the insulin concentration in serum can be below 50 pmol/L while concentrations of >70 pmol/L indicate insulin resistance and the onset of type II diabetes." (PMID 37504117, 2023). "Macrophages impair the ability to secrete insulin by β cells, thus enhancing insulin resistance, leading to hyperglycemia." (PMID 36975496, 2023). "Insulin resistance is a condition in which the body’s sensitivity and responsiveness to insulin are reduced." (PMID 37537553, 2023). "The activation of JNK in liver, adipose tissue and skeletal muscle has been shown to interfere with the transmission of insulin signaling, resulting in insulin resistance." (PMID 37510186, 2023). "The results of the current study did not prove any significant difference between the groups in terms of glucose metabolism and insulin resistance, as evidenced by the comparison of levels of glucose and insulin at points 0 and 120 min of the OGTT." (PMID 37623858, 2023). "While these are the same between models, the root causes of metabolic dysfunction vary, as WD-fed mice develop peripheral insulin resistance while WD + STZ mice possess both peripheral insulin resistance and impaired insulin secretion." (PMID 37885804, 2023).